CLN5 (CLN5 lysosomal BMP synthase)
Diseases named in the same sentence as CLN5 in open-access papers (continued):
Sharing a sentence is not in itself a finding about the gene and the disease.
Alzheimer disease (4 papers, 2020 to 2025). A progressive, neurodegenerative disease characterized by loss of function and death of nerve cells in several areas of the brain leading to loss of cognitive function such as memory and language. "CLN5 allelic variation in Alzheimer’s disease and the common pathologies of lysosome dysfunction in many other neurodegenerative diseases mean that future focus on CLN5 will likely drive our understanding of brain function more widely." (PMID 33792748, 2021). "Rare variants of NCL-related genes, such as CLN5 and CLN7, have been described as candidate risk factors for dementia, Alzheimer’s disease and Parkinson’s disease, possibly facilitating the pathogenic mechanisms underlying these diseases." (PMID 33792748, 2021). "Previous studies showed that patient-derived CLN5 mutants, such as R121P, R121H, R145P, L358AfsX4, W379C, and Y392X, and the Alzheimer’s disease-linked loss-of-function CLN5 mutant N320S, are retained at the ER rather than trafficked to lysosomes." (PMID 35921411, 2022).
retinal degeneration (4 papers, 2018 to 2025). Degeneration of the retina. "In CLN5-deficient mice, retinal degeneration is marked by early-onset photoreceptor death accompanied by retinal inflammation." (PMID 40358187, 2025). "Furthermore, the intravitreal injection of an AAV9-CLN5 vector into a CLN5 sheep model largely prevented retinal degeneration and loss of retinal function." (PMID 35509995, 2022). "This systematic study of the progression of retinal degeneration in distinct sheep models of CLN5 and CLN6 NCL has highlighted the differential vulnerability of retinal cell types in each disease and the time course of degeneration." (PMID 35256654, 2022). "Most other mouse models of NCL, including the Cln5−/− and Cln6nclf mouse, which mimics late-infantile NCL, display prominent retinal degeneration and microglia reactivity at younger ages." (PMID 30042155, 2018).
Blindness (3 papers, 2008 to 2023). Blindness is the condition of lacking visual perception defined as a profound reduction in visual perception. "Differential expression of genes relating to eye-development is interesting and expected, since blindness is the first symptom that can be observed in Cln5-/- mice." (PMID 18371231, 2008). "As the patients suffered from declining visual acuity or blindness, an involvement of the retina like in CLN1–3 and CLN5 seems possible, although an electroretinogram in one patient with TBCK-DD was normal and points to a cause by affected neurons in the central visual tract." (PMID 30591081, 2018).
late infantile NCL (3 papers, 2019 to 2025). "Biallelic mutations in the CLN7 gene cause the variant late infantile NCL (BD) as do biallelic mutations in CLN5, CLN6 and CLN8 genes." (PMID 41173878, 2025). "Studies have suggested variants of Late-Infantile NCLs (LINCLs) include the major type CLN2 and minor types CLN5, CLN6, CLN7, and CLN8." (PMID 31105743, 2019).
Atrophy (2 papers, 2023 to 2025). Any weakening or degeneration, especially through lack of use. "Overall, the volume increases, or stabilisation observed in the majority of the ICV/IVT-treated sheep contrasted the rapid atrophy seen in untreated CLN5−/− sheep, which causes an average loss of 9.4 mL of intracranial volume between 3 and 19 months of age." (PMID 37942487, 2023).
brain tumors (2 papers, 2022 to 2024). "In addition, this is the first clinical study to provide data on serum concentrations of OCLN, CLN5, and Zo-1 in patients with brain tumours during IMRT." (PMID 38337823, 2024).
Cerebral ischemia (2 papers, 2019 to 2022). Restriction of arterial blood supply to the brain associated with insufficient oxygenation to support the metabolic requirements of the tissue. "For example, blocking MMP activation or MMP-9 knock-out (KO) prevented degradation of CLN-5 and OCLN, and attenuated BBB disruption, in cerebral ischemia/reperfusion animal models." (PMID 30699952, 2019).
cognitive decline (2 papers, 2022). "They used the naturally occurring CLN5-deficient Borderdale sheep which recapitulates the key features of human CLN5 disease, such as motor and cognitive decline, progressive neurodegeneration in the brain and the retina, and loss of vision." (PMID 35509995, 2022).
experimental autoimmune encephalomyelitis (2 papers, 2016 to 2021). An autoimmune demyelinating disease of the central nervous system that is produced experimentally in animals by the injection of homogenized brain or spinal cord in Freund's adjuvant. "High-resolution 3D confocal imaging was used to highlight CLN-5 immunoreactivity in the central nervous system (CNS) and on leukocytes of mice with the neuroinflammatory condition experimental autoimmune encephalomyelitis (EAE)." (PMID 27852330, 2016).
ischemic stroke (2 papers, 2022 to 2023). A stroke disorder caused by obstruction of blood flow to the brain, due to thrombotic (local blood clot formation) or embolic (due to a blood clot or other material traveling from another site) event. "In this study increased CLN5/zo-1 ratio indicated clinical deterioration patients caused by hemorrhagic transformation of ischemic stroke." (PMID 36293204, 2022). "Thus, the significance of the ratios between the more externally expressed CLN5 and internally expressed zo-1, was found clinically useful in ischemic strokes, as well as in our study." (PMID 36293204, 2022).
lysosomal storage disease (2 papers, 2019 to 2023). A metabolic disorder caused by mutations in proteins critical for lysosomal function, including lysosomal enzymes, lysosomal integral membrane proteins, and proteins involved in the post-translational modification and trafficking of lysosomal proteins. "Typically for lysosomal storage diseases like CLN5 NCL, the earlier the treatment the better, yet the findings from early and advanced symptomatic treated sheep demonstrate dose-dependent transduction efficiency is important." (PMID 37614821, 2023).
neuroblastoma (2 papers, 2017 to 2020). Neuroblastoma (NB) is the most common solid, extracranial childhood tumor. "Finally DBH, SLC25A1, and SLC25A13 all interact with PPT1/CLN1, CLN3, and CLN5 in SH-SY5Y human neuroblastoma cells." (PMID 32430003, 2020). "For example, proteomics-based analyses in SH-SY5Y human neuroblastoma cells revealed that PPT1/CLN1, CLN3, and CLN5 interact with 23, 58, and 31 proteins, respectively." (PMID 32430003, 2020).
retinal disease (2 papers, 2023). "Robust CLN5 protein expression was detected throughout the brain and spinal cord, and improvements in central nervous system and retinal disease correlates were observed." (PMID 37942487, 2023).
Cerebellar atrophy (1 paper, 2024). Cerebellar atrophy is defined as a cerebellum with initially normal structures, in a posterior fossa with normal size, which displays enlarged fissures (interfolial spaces) in comparison to the foliae secondary to loss of tissue. "Imaging showed cerebellar atrophy, and genetic testing was positive for the CLN5 variant (c.826T > C; p.Phe276 Leu) with uncertain significance." (PMID 39525553, 2024).
cerebral amyloid angiopathy (1 paper, 2025). "Not only in AD, but ApoE4 is also associated with a high prevalence of cerebral amyloid angiopathy lesions at 32%, which is related to a reduction in CLN-5 expression." (PMID 40443793, 2025).
clear cell renal cell carcinoma (1 paper, 2021). "For example, silencing CLN5 (via RNAi) causes G0/1 arrest in HeLa cells, reduces cell number in clear cell renal cell carcinoma, and reduces the viability of HEK293 and primary endothelial cells." (PMID 34291044, 2021).
Cognitive impairment (1 paper, 2021). Abnormal cognition is characterized by deficits in thinking, reasoning, or remembering. "One of the thirteen Batten disease forms, CLN5 Batten disease, is caused by mutations in the CLN5 gene, leading to motor deficits, mental deterioration, cognitive impairment, visual impairment, and epileptic seizures in children." (PMID 34680045, 2021).
cortical blindness (1 paper, 2023). "IVT administration alone was not sufficient to prevent vision loss in CLN5−/− sheep, likely due to cortical blindness since the CNS remained untreated." (PMID 37942487, 2023).
developmental delay (1 paper, 2020). "Despite the large de novo deletion, which can be classified as a pathogenic copy number variant (CNV), the patient’s clinical presentation is mostly consistent with that of CLN5, except for early developmental delay which is believed due to the large deletion." (PMID 32393339, 2020).
Dystonia (1 paper, 2024). An abnormally increased muscular tone that causes fixed abnormal postures. "Only one case report has been reported of CLN5 variant presenting with atypical parkinsonism with dystonia." (PMID 39525553, 2024).
glioblastoma (1 paper, 2021). The most malignant astrocytic tumor (WHO grade IV). "Based on the previous results, we examined the effect of cln5-deficiency on folic acid-mediated chemotaxis since work in human cells lines (HEK-293 and U87 glioblastoma cells) supports a link between chemotaxis and autophagy, specifically autophagosome biogenesis." (PMID 34291044, 2021).
ischemia (1 paper, 2022). A hypoperfusion of the BLOOD through an organ or tissue caused by a PATHOLOGIC CONSTRICTION or obstruction of its BLOOD VESSELS, or an absence of BLOOD CIRCULATION. "Moreover, the CLN5 levels in the cerebrospinal fluid were associated with the severity of the brain damage at 24 h after ischemia." (PMID 36293204, 2022).
neuronal ceroid lipofuscinosis type 7 (1 paper, 2019). "For instance, recent proteomics analysis has revealed that one of the proteins which is markedly downregulated in neuronal ceroid lipofuscinosis type 7, is, besides MFSD8 itself, CLN5." (PMID 30548430, 2019).
obsessive-compulsive disorder (1 paper, 2019). A disorder characterized by the presence of persistent and recurrent irrational thoughts (obsessions), resulting in marked anxiety and repetitive excessive behaviors (compulsions) as a way to try to decrease that anxiety. "GWAS SNP rs11149058 is associated with Tourette syndrome and obsessive-compulsive disorder, and the target gene of the corresponding DHS containing this SNP, CLN5, was included among genes reported in GWAS analyses." (PMID 30930929, 2019).
protein deficiencies (1 paper, 2022). "Recent experimental ocular gene therapies on animal models with soluble lysosomal enzyme deficiencies (CLN1, CLN5, CLN10, and CLN11) and transmembrane protein deficiencies (CLN3 and CLN6) have shown the strong potential of gene therapeutic approaches to effectively treat NCL-related retinopathies." (PMID 35509995, 2022).
tumor (7 papers, 2016 to 2023). "Fortunately, the opposite effect to the present case was produced since the tumour development due to a VHL mutation was counteracted by a germ line mutation in heterozygous condition at the CLN5 gene." (PMID 37843608, 2023). "Particularly, in the case of VHL disease, we have published the case of a 76-year-old woman in which a mutation in CLN5 (ceroid lipofuscinosis, neuronal, 5) offers a protective effect, preventing VHL-related tumour development." (PMID 37843608, 2023). "In our differential gene expression analysis and GSEA, most enriched genes are involved in tumor aggressiveness and drug resistance including ABHD2, ABCC4, CLN5 intracellular trafficking protein, and insulin like growth factor 2 receptor." (PMID 35054064, 2022). "An experimental study demonstrated that NEU1 siRNA can significantly suppress proliferation, apoptosis, and invasion of tumor cells by targeting lysosomal membrane proteins (CLN3 and CLN5)." (PMID 34513919, 2021). "In this respect, CLN-5+ EVs released from BMEC might “educate” leukocytes in migratory behavior, paralleling what EVs from tumor cells have been shown to do in stimulating mobilization of bone marrow progenitor cells out of their niche." (PMID 27852330, 2016).
neurodegenerative disease (4 papers, 2008 to 2025). A disorder of the central nervous system characterized by gradual and progressive loss of neural tissue and neurologic function. "Like several other neurodegenerative diseases showing disturbed lipid metabolism, CLN5 deficiency also results in an altered serum lipid profile." (PMID 33792748, 2021).
retinopathies (2 papers, 2017 to 2022). "Indeed, we observed a statistically significant thinning of INL and IPL in CLN5 deficient mice occurring in an advanced stage of retinopathy." (PMID 28487519, 2017). "In this study, we thoroughly characterized the retinopathy in CLN5 deficient mice." (PMID 28487519, 2017).
genetic disorder (1 paper, 2012). "Specifically, an incompletely penetrant POLG1 change (p.Gly517Val) in combination with CLN5 mutations produced a clinical phenotype in the proband far earlier than that reported for either genetic disorder alone." (PMID 22727047, 2012).
infection (1 paper, 2017). The state of being infected such as from the introduction of a foreign agent such as serum, vaccine, antigenic substance or organism. "Fibroblasts from the CLN5 patient were reprogrammed by the expression of SOX2, OCT3/4, KLF4 and MYC after infection with a Sendai virus delivery vector, in order to produce integration-free CLN5Y392X iPSCs." (PMID 28468312, 2017).
neurological disease (1 paper, 2023). "Indeed, the single administration of brain-directed lentiviral or recombinant adeno-associated virus 9 (AAV9) vectors expressing ovine CLN5 to CLN5 affected sheep resulted in long-term neurological disease attenuation." (PMID 37614821, 2023).
vascular disorder (1 paper, 2017). A general term used to describe any disease affecting blood vessels]. "Complexes such as Bcl3/NF-kappaB2 complex (governed by BCL3 and NFKB2), vacuolar lumen (governed by CLN5), IPAF inflammasome complex (CASP1, CASP4, NLRC4) help to understand the involvement of inflammation and vascular disorder in AD." (PMID 28199395, 2017).
CLN5 also shares sentences with these, for which no sentence is quoted: multiple sclerosis (3 papers); placental insufficiency (2); amyotrophic lateral sclerosis (1); Ataxia (1); bladder cancer (1); cancer (1); colitis (1); congenital adrenal hyperplasia (1); demyelinating disease (1); epileptic seizures (1); inflammation (1); Kaya-Barakat-Masson syndrome (1); Krabbe disease (1); neuronal ceroid lipofuscinosis 5 (1); Onset (1); Osteopenia (1); Parkinson disease (1); preeclampsia (1); sphingolipidoses (1); Tay-Sachs disease (1); Tourette syndrome (1); Visual impairment (1); Wolman disease (1).